SEMA7A (semaphorin 7A (JohnMiltonHagen blood group))
Diseases named in the same sentence as SEMA7A in open-access papers (continued):
Sharing a sentence is not in itself a finding about the gene and the disease.
pulmonary fibrosis (13 papers, 2013 to 2025). Chronic progressive interstitial lung disorder characterized by the replacement of the lung tissue by connective tissue, leading to progressive dyspnea, respiratory failure, or right heart failure. "The loss of SEMA7A has been shown to attenuate the development of pulmonary fibrosis in a murine model of bleomycin-induced pulmonary fibrosis." (PMID 38646784, 2024). "Sema7A has been reported to associate with activity-dependent olfactory synapse formation, pulmonary fibrosis, multiple sclerosis, T-cell-mediated inflammatory responses, and breast tumor progression." (PMID 32826874, 2020). "In patients with idiopathic pulmonary fibrosis (IPF), the expression of SEMA7A on CD4+CD25+FoxP3+ regulatory T cells (Tregs) is associated with disease progression." (PMID 40182927, 2025). "A pulmonary fibrosis study showed that expression of Sema7A and its receptors, Plexin C1 and α1β1 integrins, are induced by TGF-β1 contributing to TGF-β1-derived fibrosis and tissue remodeling mediated by the PI3K/AKT pathway." (PMID 32210960, 2020). "Sema7A knockout mice crossed with TGF-β1 overexpressing transgenic mice exhibited decreased severity in lung fibrosis compared to TGF-β1 overexpressing transgenic control mice." (PMID 32210960, 2020). "Previous studies demonstrated that TGF-β1 promotes the secretion of Sema7A and induces pulmonary fibrosis and multiple sclerosis." (PMID 32826874, 2020). "For example, Sema7a-knockout mice are resistant to inflammation and it has been described that Sema7A is an important molecule in the pathogenesis of lung fibrosis, exacerbating fibrosis via binding to β1-integrin." (PMID 24324469, 2013). "The upregulation of SEMA7A may exacerbate pulmonary fibrosis and reflect disease severity, suggesting its potential as a diagnostic marker for pulmonary tuberculosis." (PMID 40182927, 2025). "Collagen-producing fibrocytes and B cells expressing Sema7A contribute to pulmonary fibrosis and thus could lead to SSc." (PMID 32210960, 2020). "Additionally, TGFβ is known to positively regulate SEMA7A in pulmonary fibrosis, where SEMA7A is critical for ECM deposition via activation of the PI3K/AKT pathway." (PMID 30847405, 2019). "During T-cell mediated inflammation, SEMA7A was shown to mediate its effect through ITGA1/ITGB1 integrin receptor and, during pulmonary fibrosis, through ITGB1 integrin." (PMID 38094294, 2023). "One study showed that Sema7a expression is stimulated by TGF-β1 in the murine lung, with Sema7a being a critical regulator of tissue remodeling in TGF-β1-induced pulmonary fibrosis." (PMID 38022556, 2023).
melanoma (11 papers, 2015 to 2025). A malignant, usually aggressive tumor composed of atypical, neoplastic melanocytes. "On the contrary, Sema6A positively correlates with melanoma migration and Sema7A is associated with melanoma metastasis." (PMID 30454024, 2018). "Recent studies have shown that the upregulation of SEMA7A expression is significantly associated with multiple sclerosis, systemic sclerosis–related interstitial lung disease, rheumatoid arthritis, airway inflammation, colitis, systemic lupus erythematosus, and melanoma and other cancers." (PMID 35938531, 2022). "Our demonstration that Type I IFNs mediate their anti-melanoma effects, at least in part, by inhibiting the Sema7a-Chi3l1 pathway raises the interesting possibility that the Sema7a-Chi3l1 axis plays an important role in the immunoediting response." (PMID 27198666, 2016). "In addition, the expression levels of SEMA7A are positively related to the pulmonary metastasis in a melanoma murine model." (PMID 41019072, 2025). "SEMA7A participates as a tumoral suppressor protein in melanoma progression." (PMID 26378920, 2015). "Of note, in agreement with finding demonstrating absence of detectable Sema7A protein in a panel of human melanoma cell lines, the analysed melanoma tissues resulted prevalently negative for this semaphorin." (PMID 33858502, 2021).
atherosclerosis (9 papers, 2018 to 2025). A disease characterized by the build-up of fatty material and calcium deposition in the arterial wall resulting in partial or complete occlusion of the arterial lumen. "The causal role of Sema7A in experimental atherosclerosis urges a translational outlook into its clinical relevance." (PMID 30555351, 2018). "In this study, we investigated the role of Sema7A underlying angiogenesis in atherosclerosis using a knockout mice model and EC Sema7A expression system." (PMID 30555351, 2018). "In summary, our results demonstrated that increased serum Sema7A was independently associated with the risk of AAS, showing that Sema7A may play an important role in atherosclerosis." (PMID 30729666, 2019). "A previous study reported that Sema7a and its receptor Integrin-β1 contributed to vascular endothelial cell injury and the pathophysiology of atherosclerosis." (PMID 38022556, 2023). "Semaphorin 7A (Sema7A), a neural guidance cue, was recently identified to regulate atherosclerosis in mice." (PMID 30729666, 2019). "We demonstrated an important result that elevated Sema7A was highly associated with AAS, which provided strong support to our previous findings in animal models of atherosclerosis." (PMID 30729666, 2019). "Targeted Sema7A gene knockout protected mice from high‐fat diet and disturbed blood flow‐induced atherosclerosis." (PMID 30729666, 2019). "It is well documented that Sema7A and its receptors are expressed in leucocytes, endothelial cells (ECs), neurons and platelets, all of which play essential roles in atherosclerosis." (PMID 30729666, 2019). "In our recent study, we found that Sema7A expression was up‐regulated in an experimental mouse atherosclerosis model." (PMID 30729666, 2019). "Like Sema4A, Sema4D, Sema3A, and Sema7A, reported to participate in atherosclerosis, are also widely investigated in immune cells." (PMID 30405423, 2018). "They concluded that Sema7A upregulation by d-flow mediates endothelial dysfunction and atherosclerosis in a β1 integrin-dependent manner." (PMID 30405423, 2018). "We recently demonstrated that Sema7A mediates d-flow-induced endothelial dysfunction and promotes atherosclerosis, and deletion of Sema7A significant reduces atherosclerotic plaque formation." (PMID 30555351, 2018). "Together, our findings show that Sema7A promotes VEGFA/VEGFR2-mediated neovascularization in a β1 integrin-dependent manner, supporting a crucial role of Sema7A in the progression of human atherosclerosis." (PMID 30555351, 2018). "The reduction of plaque neovascularization by Sema7A deletion suggested a pro-angiogenesis role of Sema7A during atherosclerosis." (PMID 30555351, 2018). "Moreover, a recent study underlined the potential role of Sema7A in promoting VEGFA/VEGFR2-mediated neovascularization in ApoE-/- mice, supporting a pivotal role of Sema7A in the progression of human atherosclerosis and IPH." (PMID 38673936, 2024). "Therefore, Sema7A plays an essential role in the development of atherosclerosis via multiple pathways." (PMID 35045890, 2022). "Given a pro-angiogenic role of Sema7A in tumor and corneal cells, we asked whether it mediates neovascularization in atherosclerosis." (PMID 30555351, 2018). "Studies showed that Sema7A mediates atherosclerosis, retinal angiogenesis, and tumor growth." (PMID 30555351, 2018). "However, the role of Sema7A in angiogenesis during the development of atherosclerosis remains unclear." (PMID 30555351, 2018).
multiple sclerosis (9 papers, 2014 to 2024). A progressive autoimmune disorder affecting the central nervous system resulting in demyelination. "To date, increased systemic or tissue levels of Sema7A have been associated with a spectrum of inflammatory disorders, including multiple sclerosis, interstitial lung disease, rheumatoid arthritis, and airway allergy." (PMID 30555351, 2018). "Secreted semaphorins could be drug targets for neurodegenerative diseases; for instance, Sema4D antibody was used to rescue cognitive dysfunctions in a mouse model of Huntington disease, and depletion of Sema7A has been suggested as a possible treatment for multiple sclerosis." (PMID 37316917, 2023). "SEMA7A, shown here to be upregulated in CB of AD brains, is known to be involved in repair of the glial scar following spinal cord injury and to play a role in the development of multiple sclerosis, but has not previously been linked to the disease process in AD43." (PMID 30729181, 2019). "SEMA7A is the only GPI-anchored semaphorin which plays a role in varied inflammatory diseases such as skin inflammation, corneal inflammation, multiple sclerosis, and liver fibrosis." (PMID 35955933, 2022).
rheumatoid arthritis (8 papers, 2017 to 2024). A chronic, systemic autoimmune disorder characterized by inflammation in the synovial membranes and articular surfaces. "We examined the role of Sema7A in modulating cellular immune responses and to provide experimental data validating the therapeutic potential of Sema7A in rheumatoid arthritis (RA)." (PMID 28109308, 2017). "Finally, several genes (SEMA7A, CSK, GUCY1A2, EMCN, OPRM1) are associated with rheumatoid arthritis (RA)." (PMID 36658473, 2023). "The chemokines CXCL1 and CXCL6 are chemotactic cytokines involved in various pathological processes including inflammatory diseases, and it has been shown that both CXCL1, CXCL6, and SEMA7A are involved in the inflammatory response in joint-related diseases such as rheumatoid arthritis." (PMID 32434555, 2020).
glioma (7 papers, 2019 to 2025). A benign or malignant brain and spinal cord tumor that arises from glial cells (astrocytes, oligodendrocytes, ependymal cells). "The research described that Semaphorin 7A (SEMA7A) was exposed to the surface of patient-derived glioma-associated stem cells (GASC) EVs and increased the activity of GSC through the interaction between integrin β1 and GSC in the microenvironment." (PMID 33670924, 2021). "Experiments have shown that exosomes secreted by glioma-associated stem cells increase the invasiveness of GSSCs and GBM cell lines in vitro, which is related to Semaphorin7A (SEMA7A) in glioma-associated stem cells." (PMID 36727049, 2022).
breast tumor (6 papers, 2019 to 2026). "In normal breast tissue Sema7A is almost absent, while its expression increases in breast tumor samples, and it is associated with decreased overall patient survival." (PMID 33537086, 2021). "Clinically, breast tumours positive for lymph vessel invasion showed higher SEMA7A expression, in the METABRIC dataset, again linking SEMA7A to lymphangiogenesis and implicating SEMA7A in the stimulation of dissemination via the lymphatics." (PMID 37685898, 2023). "In this review, we will highlight the similarities between involution and cancer in the mammary gland, and further define the contribution of SEMA7A/COX-2/collagen interplay to postpartum involution and breast tumor progression and metastasis." (PMID 30847405, 2019).
Stroke (6 papers, 2019 to 2025). Sudden impairment of blood flow to a part of the brain due to occlusion or rupture of an artery to the brain. "In the case of stroke, serum Sema7A levels have been associated with risk of morbidity, whereas serum CD163 has been reported to be negatively associated with prognosis." (PMID 38373967, 2024). "Subsequently, we conducted a study to investigate the association of serum Sema7A with atherothrombotic stroke and showed that elevated level of Sema7A is independently associated with atherothrombotic stroke." (PMID 35350431, 2022). "The aim of this study was to investigate the association between serum Sema7A and the risk of acute atherothrombotic stroke (AAS)." (PMID 30729666, 2019). "Based on previous studies, we postulated that there are differences in Sema7A/CD163 expression between different stroke subtypes and prognosis." (PMID 38373967, 2024). "In short, Sema7A/CD163 has potential as a prognostic marker for stroke, but more rigorous studies are still needed to validate the conclusions." (PMID 38373967, 2024). "Sema4D and Sema7A signaling mainly participates in inflammatory response in pericytes and microglial cells after stroke." (PMID 35350431, 2022). "Only one study has described a relationship between Sema7A and stroke." (PMID 38373967, 2024). "However, both Sema7A (OR, 2.017; 95% CI, 1.301–3.518; p = 0.005) and CD163 (OR, 2.283; 95% CI, 1.252–5.724; p = 0.03) were associated with the poor prognosis for stroke, after adjusting for stroke severity." (PMID 38373967, 2024). "In general, current studies on Sema7A/CD163 and stroke are mainly based on serum and arterial components." (PMID 38373967, 2024). "Our study discusses the relationship between Sema7A/CD163 and stroke etiology and prognosis based on thrombus samples." (PMID 38373967, 2024). "We compared the levels of Sema7A and CD163 between these groups and analyzed their relationships with stroke severity, hemorrhagic transformation and prognosis." (PMID 38373967, 2024). "In this study, we investigated the relationship between Sema7A/CD163 expression in thrombi and stroke classification, along with other clinical characteristics." (PMID 38373967, 2024). "The relationship between Sema7A/CD163 expression in thrombus components and stroke etiology and prognosis remains unclear." (PMID 38373967, 2024).
colitis (5 papers, 2021 to 2025). Inflammation of the colon. "It is noteworthy that Sema7a has been recognized for its role in stimulating colon macrophages to produce IL-10, aligning with previous research which attributes anti-colitis effects to Sema7A." (PMID 38308210, 2024). "It’s worth emphasizing that Sema7a, a hub mRNA, plays a part in anti-colitis effects by stimulating macrophage IL-10 production." (PMID 38308210, 2024).
fibrosis (5 papers, 2014 to 2023). the formation of excess fibrous connective tissue in an organ or tissue in a reparative or reactive process. "Several works have shown that mice deficient in Sema7A have lower disease severity in different models of fibrosis, thus suggesting that Sema7A plays a pro-fibrotic role in the pathology of SSc." (PMID 30654587, 2019). "In a murine fibrosis model, TGF-β1 has been reported to induce the expression of Sema7a in the murine lung." (PMID 38022556, 2023). "In a murine fibrosis model, TGF-β has been reported to induce the expression of SEMA7A in the murine lung." (PMID 24550834, 2014).
experimental autoimmune encephalomyelitis (4 papers, 2021 to 2023). An autoimmune demyelinating disease of the central nervous system that is produced experimentally in animals by the injection of homogenized brain or spinal cord in Freund's adjuvant. "The last implicated protein with an immunological function is SEMA7A, known to be involved in T-cell-mediated inflammation, and associated with more inflammatory lesions and demyelination in MS and experimental autoimmune encephalomyelitis." (PMID 36154753, 2023).
glioblastoma (4 papers, 2015 to 2025). The most malignant astrocytic tumor (WHO grade IV). "Moreover, SEMA7A is expressed in the secretome of U87 glioblastoma cells at higher level than in less aggressive and invasive cell lines (T98, U118)." (PMID 31151295, 2019). "We observed that SEMA7A is expressed in the cells, but not released in vesicles produced by the healthy cell type, suggesting that the release of SEMA7A in exosomes is a peculiarity of mesenchymal stromal cells resident in the glioblastoma microenvironment." (PMID 31151295, 2019).
liver fibrosis (4 papers, 2022 to 2025). "This protective finding is also different to chronic hepatic injury models, such as CCl4-induced liver injury, where Sema7a promotes hepatic fibrosis and Il6 and Ccl2 expression." (PMID 40114253, 2025).
lung injury (4 papers, 2016 to 2025). "Semaphorin 7a (Sema7a) is expressed on hepatocytes in a circular ring surrounding necrotic cells during acute liver injury, and circulatory levels correlate with damage." (PMID 40114253, 2025). "Previous studies have also demonstrated that deletion of SEMA7A has an anti‐inflammatory effect on seawater aspiration‐induced acute lung injury, collagen‐induced arthritis, myocardial tissue injury, and coxsackievirus B3‐induced viral myocarditis." (PMID 36705403, 2023). "Both SEMA3F and SEMA7A are secreted by activated immune cells and have emerged as regulators of neutrophil migration, vascular permeability and cytoskeletal remodeling, and the initiation of an inflammatory signaling cascade in models of acute lung injury." (PMID 37893159, 2023).
myocardial ischemia (4 papers, 2020 to 2023). A disorder of cardiac function caused by insufficient blood flow to the muscle tissue of the heart. "SEMA7A has also been reported to regulate cytokine-induced memory-like responses in human natural killer cells, and erythrocyte-derived SEMA7A has been shown to induce thrombotic inflammation in myocardial ischemia/reperfusion injuries." (PMID 37958549, 2023). "The profound increase in Sema7a in plasma of patients and mice with myocardial ischemia raised the possibility that it has a functional role in the progression of myocardial IR injury." (PMID 32161256, 2020). "Experiments in mice revealed that plasma Sema7a increased very rapidly during cardiac ischemia, with a significant elevation detected as early as after 1 min of reperfusion." (PMID 32161256, 2020). "Recently, Sema7A was reported to regulate cytokine-induced memory-like responses in human natural killer cells, and erythrocyte-derived Sema7A was shown to induce thrombosis inflammation in myocardial ischemia/reperfusion injuries." (PMID 33637648, 2021). "In summary, Sema7a has a significant impact on myocardial ischemia/reperfusion injury." (PMID 32161256, 2020).
pancreatic cancer (4 papers, 2021 to 2023). "LOXL1-AS1 promoted pancreatic cancer by promoting the expression of Semaphorin 7A (SEMA7A) and sequestering it away from miR-28-5p." (PMID 34178644, 2021). "For example, lncRNA LOXL1-AS1 facilitated the progression of pancreatic cancer through regulating miR-28-5p and SEMA7A." (PMID 34516335, 2021).
lung carcinoma (3 papers, 2017 to 2023). "Semaphorin 7A (SEMA7A), a GPI-AP, has been found to promote EGFR-tyrosine kinase inhibitor (TKI) resistance in EGFR-mutated lung cancer through activating the mTOR pathway." (PMID 31118109, 2019).
oral cancer (3 papers, 2015 to 2025). "In conclusion, we explored the biologic role of SEMA7A in human oral cancer in the current study." (PMID 26378920, 2015).